IDH1 (isocitrate dehydrogenase (NADP(+)) 1)
Diseases named in the same sentence as IDH1 in open-access papers (continued):
Sharing a sentence is not in itself a finding about the gene and the disease.
glioma (continued). "Recent studies have shown that the presence of IDH1-R132H mutation is associated with a better prognosis in glioma patients in association to the decrease in the expression of the WNT/β-catenin pathway." (PMID 34070746, 2021). "The risk level separated by the risk score reflected the multi-omics alteration: IDH1 mutation, the most common mutation in glioma, was involved mainly in the low-risk group." (PMID 34093830, 2021). "IDH1 mutation has been reported to be a strong and independent indicator for good prognosis in gliomas whatever the tumor grade." (PMID 34070746, 2021). "ATRX and IDH1/2 mutations co-occur frequently in glioma, and we and others have reported that the latter induce HR defects and PARP inhibitor sensitivity." (PMID 34118569, 2021). "The presence of D-2-HG in IDH1/2 mutated gliomas induced inhibition of KDM4A, which decreases the half-life and protein level of DEPTOR, and further enhances mTORC1/2 kinase activities." (PMID 34571995, 2021). "In terms of molecular pathology, the risk score was found to be much higher in IDH1 wild-type gliomas." (PMID 33324981, 2021). "Some molecular markers were developed for glioma, and some biomarkers are used clinically, such as IDH1 mutation and 1p/19q co-deletion." (PMID 34638749, 2021). "To address this in a model amenable to experimental manipulation, we turned to patient-derived glioma stem-like cells (GSCs) carrying the endogenous IDH1 mutation (NCH1681, NCH551b, NCH612) and control cells of IDHwt GBM (NCH644, NCH601, NCH421k)." (PMID 34250481, 2021). "Since non-R132H IDH1/2-mutated gliomas have increased DNA methylation levels, we compared the overall survival of patients with different IDH mutations." (PMID 33740099, 2021). "Currently, AG-120 is under phase 3 clinical trial (NCT03173248) in AML, and phase 1 clinical trial (NCT02073994) in advanced solid tumors with IDH1 mutation, including glioma." (PMID 34571995, 2021). "The application of intravoxel incoherent motion diffusion weighted imaging (IVIM-DWI) in differentiating glioma grading and IDH1 mutation status were poorly investigated." (PMID 33795525, 2021). "A number of IDH1 and IDH2 mutations have been reported in glioma, with the most common a base substitution in codon 132 of IDH1 resulting in an arginine to histidine replacement (IDH1R132H)." (PMID 33842321, 2021). "The concentration of R-2HG metabolite in glioma cells carrying the mutated IDH1/2 can reach ~30 millimolar saturating the mitochondrial R-2HG dehydrogenase responsible for its cellular removal." (PMID 34070384, 2021). "Most studies have demonstrated that IDH1 mutation plays a key role in the tumorigenesis and progression of glioma by DNA hypermethylation, histone hypermethylation, hypoxia-inducible factor-1a level changes, and oxidative stress mechanisms." (PMID 35111661, 2021). "dMRI has great potential to provide imaging markers that are sensitive to microstructural changes in gliomas caused by IDH1 mutation and cell proliferation, thereby facilitating prognostic prediction and treatment of glioma patients." (PMID 34880724, 2021). "In gliomas, heterozygous mutations in IDH1 occur exclusively at residue R132, which is usually changed to a histidine." (PMID 34503108, 2021). "In grade II/III gliomas carrying IDH1/2 mutations, 2HG concentrations have been found between 1 and ∼30 mM." (PMID 34222022, 2021). "Although this is related to the uneven distribution of IDH1 mutation status in gliomas, future prospective studies with large samples are needed to ensure the accuracy of the experiment." (PMID 34880724, 2021). "IDH1 inhibitor amplified the efficiency of glioma-associated antigens vaccination, augmented the infiltration of CD8 + T cell and improved the survival of mice challenged with IDH1mt tumor." (PMID 33842477, 2021). "A few studies have investigated the association of IDH-1 status with morphological MRI analysis in low grade gliomas." (PMID 33868245, 2021).
glioma (continued). "Mutations in gliomas often occur in IDH1 and IDH2, both of which caused the conversion of α-ketoglutarate (α-KG) to 2-hydroxyglutarate (2-HG) in a NADPH-dependent manner." (PMID 34211978, 2021). "Previous series strongly suggest that patients with IDH2 mutated glioma more frequently host a 1p19q codeletion than those with IDH1 alterations." (PMID 33669525, 2021). "In clinical studies, IDH1/2 mutations were observed in low-grade glioma and secondary glioblastoma (∼80%), and in acute myeloid leukemia (∼20%), angioimmunoblastic T-cell lymphomas (16%–17%) with worse prognosis." (PMID 35006438, 2021). "Two mutation (IDH1/2 mutations and 1p19q co-deletion) tests have become a part of the routine diagnosis and classification of gliomas." (PMID 34830775, 2021). "Several GWAS and GWAS meta‐analyses have identified 20q13.33 as a risk locus, especially its association with isocitrate dehydrogenase 1 (IDH1) wild‐type or TERT (telomerase reverse transcriptase)‐only gliomas." (PMID 33169458, 2021). "The CpG-island methylator phenotype (G-CIMP) is closely related with IDH1 mutation and is associated with better prognosis in gliomas." (PMID 34168976, 2021). "Testing was performed on glioma samples as part of clinical care and analyzed up to 395 cancer-associated genes (including IDH1/2)." (PMID 33778493, 2021). "Mutant IDH1 gliomas are sub-classified, according with the loss of 1p/19q chromosomal segments, in mutant IDH1-1p/19q-codel and mutant IDH1-noncodel." (PMID 33790740, 2021). "R132H IDH1 mutations occur early in the development of glioma and display neomorphic activity that converts α-ketogluterate to 2-hydroxyglutarate (2-HG)." (PMID 34828344, 2021). "Secondary glioblastomas (defined as harboring IDH1 mutation or previous lower grade glioma) included 35 patients (5%)." (PMID 33718145, 2021). "The presence of 1p19q codeletion with IDH1/2-mutant gliomas defines oligodendroglioma and is associated with “poorly circumscribed” margins, slight frontal lobe predilection, heterogeneous T1 and T2 signals, and lower ADC values." (PMID 34676470, 2021). "These gene expression statuses were also strongly correlated with the prognosis of the glioma patients; particularly, low expression levels were observed in patients with IDH1 mutation." (PMID 34584069, 2021). "In the present study, the IDH1 mutation status of gliomas and the peritumoral brain edema volume were two independent factors associated with the ALPS index." (PMID 34631582, 2021). "Twenty patients had an IDH1 mutation, including 14 cholangiocarcinoma, 3 glioma and 3 chondrosarcoma patients." (PMID 34069550, 2021). "In our previous research, we demonstrated that IDH1 mutation occurs frequently and predicts favourable prognosis in Chinese glioma patients." (PMID 33663520, 2021). "Univariate logistic regression analysis showed that age at diagnosis, KPS, tumor grade, glioma type, tumor location, EOR, co-CT, ad-CT, and IDH1 were significantly associated with short-term glioma recurrence." (PMID 34778058, 2021). "IDH mutations identified in gliomas tend to occur at the active site of the enzyme at arginine 132 and 172 in IDH1 and IDH2, respectively." (PMID 34675774, 2021). "Although initial reports suggested that G-CIMP remains stable during disease progression, more recent analyses have shown their loss upon recurrence of IDH1-mutant gliomas." (PMID 33842321, 2021). "IDH1 mutations are present in a large fraction or even all cancer cells in glioma, rendering IDH1 mutations an interesting target for treatment, because the high molecular homogeneity diminishes the risk of therapy resistance." (PMID 34069550, 2021). "For instance, the mutation status of isocitrate dehydrogenase (IDH)-1/2 gene and 1p/19q codeletion status are two molecular parameters in classifications of gliomas." (PMID 33435205, 2021).
glioma (continued). "This is consistent with the univariate and multivariate Cox regression analyses in our study, which demonstrated that IDH1 mutation status was an independent favorable biomarker for overall survival of glioma patients in both CGGA and TCGA datasets." (PMID 34722888, 2021). "Glioma patients that present a somatic mutation in the isocitrate dehydrogenase 1 (IDH1) gene have a significantly better prognosis and overall survival than patients with the wild-type genotype." (PMID 34503108, 2021). "IDH1 mutations are considered to occur early during the genesis of glioma, persisting during progression to secondary GBM, but they rarely appear in primary GBM." (PMID 33842321, 2021). "This strongly suggests that the Neural G0 cell state is associated with patient survival variance independently from the common glioma survival‐associated covariates (tumor grade, IDH1/2)." (PMID 34101353, 2021). "Third, our study revealed that the composition and gene function of oral microbiota were significantly associated with the IDH1 mutation in glioma, which can be used to predict the prognosis of glioma patients." (PMID 34733261, 2021). "In both immortalized astrocytes and glioma cells, IDH1 mutation and ATRX deficiency together lead to similar levels of PARP inhibitor sensitivity compared to the individual mutations, suggesting an epistatic interaction." (PMID 34118569, 2021). "We also found significant enrichments of EGFR-mutated IDHwt (FDR = 7.03E-10) and IDH1-mutated IDHmut-codel gliomas (FDR = 0.020) in later-onset cases." (PMID 34788626, 2021). "Triptolide, a potent Nrf2 inhibitor, has been shown to effectively suppress patient-derived IDH1-mutated glioma cells and exhibited selective cytotoxicity to preclinical glioma xenograft with IDH1 mutations." (PMID 34425876, 2021). "2-Hydroxyglutarate is a well-known oncometabolite produced in high quantities by mutated IDH1/2 in gliomas." (PMID 34911437, 2021). "By sequestering NAD+ in stabilised PAR chains, PARG inhibition was recently shown to cause metabolic catastrophe in glioma cell lines harbouring IDH1 mutations." (PMID 34656146, 2021). "There appears to be an even distribution of IDH1&2 mutations at low levels (less than 10%) in human cancers apart from high levels (80%) of IDH1 mutations in human low grade glioma." (PMID 34854890, 2021). "The high-frequency IDH1/2 mutations in glioma have paradoxical implications to glioma diagnosis, management, and therapy: the IDH1/2 mutation promotes malignant transformation of primary glioma, while it provides a potential anti-tumor advantage." (PMID 34571995, 2021). "Except for gliomas, acute myeloid leukemia was the only cancer with a high incidence of IDH1 mutations." (PMID 34961815, 2021). "Vaccines have also been developed targeting the IDH1 subtype of gliomas, consisting of the IDH1 (R132H)-mutated peptide, which is present in <15% of GBM patients." (PMID 34298615, 2021). "Among them, IDH1 is most frequently mutated in gliomas and harbors a monoallelic missense mutation of arginine to histidine at position 132 (IDH1R132H) at the catalytic site of the enzyme." (PMID 34067729, 2021). "Studies have shown that the IDH1/2 mutations is closely associated with DNA methylation in gliomas genomes." (PMID 33828990, 2021). "Most of the HDAC family significantly correlated with the glioma grade, IDH1 mutation, and 1p/19q codeletion." (PMID 34540896, 2021).
glioma (continued). "Since the initial discovery of mutations in the IDH1 by whole-genome sequencing in a large subset of human gliomas and AML patients, there has been a focus on understanding the consequences of mutations in IDH genes and their roles in tumor progression." (PMID 34946913, 2021). "The present clinical trial investigated the safety and maximum tolerated dose (MTD) of the combination therapy of metformin and chloroquine in patients with IDH1-mutated chondrosarcoma, glioma and intrahepatic cholangiocarcinoma." (PMID 34069550, 2021). "IDH1 mutation is considered as an early event in glioma-genesis, and has gained major importance in the 2016 WHO classification of diffuse gliomas." (PMID 34220689, 2021). "IDH1/2 mutations have been found in gliomas, hematological malignancies, and other tumors such as cholangiocarcinoma, melanoma, prostate cancer, and thyroid carcinoma." (PMID 31935911, 2020). "In patients with gliomas, isocitrate dehydrogenase 1 (IDH1) mutation status has been studied as a prognostic indicator." (PMID 33121211, 2020). "Around 90% of IDH-1 mutated (IDHmut) gliomas involve a substitution in the catalytic site of arginine-132, which is replaced by histidine (IDH1 R132H mutation)." (PMID 33212941, 2020). "They reported that glioma cells with IDH1 mutations cannot be cultured in vitro because of their death in standard cell culture condition." (PMID 33221817, 2020). "The presence of the IDH1 mutation is a valuable diagnostic, prognostic and predictive biomarker for the management of patients with glial tumours." (PMID 33302429, 2020). "This shows that both PCR–RFLP and IDH1 R132H IHC have excellent sensitivity and specificity for the detection of IDH1 mutations in glioma patients." (PMID 33247679, 2020). "In our cohort, 35% of grade III glioma patients had IDH1 mutation and the global incidence varies according to region." (PMID 32005184, 2020). "It ought to group gliomas into different grades to investigate the relationship between IDH1 mutation and prognosis." (PMID 32582544, 2020). "In one retrospective study involving gliomas that were tested for IDH1/2 mutations, gliomas with wild type IDH1/2 had a cumulative incidence of VTE of 26% compared to none with mutated IDH1/2." (PMID 32707653, 2020). "In patients with gliomas, those with IDH1 mutations, specifically IDH1 R132H, are associated with better prognosis when compared to those with IDH1 wildtype." (PMID 33121211, 2020). "In contrast, the common IDH1 (R132H) mutation is known to induce a hypermethylation phenotype in gliomas by silencing MGMT (and other mismatch repair [MMR] genes) thus sensitizing the tumor to TMZ-induced mutagenesis." (PMID 31376079, 2020). "FTL expression was enriched in high grade glioma (HGG) and its expression significantly associated with IDH1/2 wildtype and unfavorable prognosis of glioma patients." (PMID 32677981, 2020). "Several molecular biomarkers for gliomas have been identified in recent decades, including IDH1 mutation, 1p/19q deletion, MGCT promoter methylation and EGFRvIII, among others." (PMID 32692766, 2020). "It has been shown that overexpression of mutant IDH1 in primary cultures of human astrocytes induces specific histone alterations that cause DNA hypermethylation and methylome remodeling, inducing the glioma CpG island methylator (G-CIMP) phenotype." (PMID 32570988, 2020). "It is known that the IDH1/2 mutation leads to hypermethylation, which is the molecular basis of the CpG island methylator phenotype in gliomas." (PMID 33489866, 2020). "IDH1 mutant R132H (amino acid substitution at arginine 132 account for >95% IDH1 mutation in glioma), is further confirmed to induce the methylome which mirrors G-CIMP in human normal astrocytes." (PMID 32051553, 2020). "IDH1 mutations in gliomas caused leukocyte chemotaxis downregulation, resulting in suppression of the tumor-associated immune system." (PMID 32986017, 2020).
glioma (continued). "This study aimed to compare IHC, DNA sequencing, and PCR–RFLP in detecting IDH1 mutation in gliomas." (PMID 33247679, 2020). "The BRAFAMP and IDH1/2WT genotype was found to be an independent predictive factor for glioma with BRAF mutation and BRAFAMP using Cox proportional hazard regression analysis (HR = 0.138, P = 0.018)." (PMID 33489866, 2020). "Central chondrosarcoma and cholangiocarcinoma predominantly harbour R132C mutations in IDH1 (50%), glioma has mainly R132H mutations in IDH1 (90%) and AML has most often R140Q mutations in IDH2 (30–50%)." (PMID 31728625, 2020). "Mutations in IDH1, which are frequent in adult gliomas, are only found in a small proportion of pHGGs." (PMID 33585252, 2020). "Previous studies have indeed shown the association of IDH1 mutation with histology and grading of gliomas." (PMID 32856857, 2020). "IDH1 mutations are associated with certain clinicopathological and prognostic profiles in Indonesian patients with gliomas." (PMID 32856857, 2020). "This phenomenon is sustained by an enhanced amount of DNA damage in IDH1-mutated malignant glioma cells and thereby IDH1/2 mutations operate as driver mutations in glioma carcinogenesis, although their primary role is still unexplored." (PMID 33552543, 2020). "IDH1/2 mutations proved as independent prognostic factors in glioma and correlated with MGMT methylation for better survival." (PMID 33552543, 2020). "IDH2 mutations rarely occur in gliomas and are commonly limited to IDH1 mutations (Dunn, Andronesi, & Cahill, 2013)." (PMID 32146731, 2020). "Based on this analysis, the authors were capable of building a polygenic risk score that predicted not only risk to glioma but, specifically, to IDH1‐driven glioma." (PMID 32239503, 2020). "In this study, 30.8% of grades II and III gliomas harbor IDH1 mutation compared to 13% in the grades I and IV glioma group." (PMID 32856857, 2020). "Chinese Glioma Cooperative Group (CGGA) data also indicated that the IDH1 mutation led to a superior OS in glioma." (PMID 32986017, 2020). "Nearly 80% of World Health Organization Grades II and III gliomas show the presence of mutation in the IDH1 and IDH2 genes that regulate the omonimous enzymes." (PMID 33178960, 2020). "Somatic mutation at codon 132 of IDH1 gene, is prevalent in WHO grade II or III gliomas and in the secondary glioblastomas, and it is associated with better outcome than those patients with IDH1 wild-type." (PMID 33282092, 2020). "All the detected differential phosphatidylserine molecules were increased in IDH-1 mutation glioma, but sphingolipid was decreased." (PMID 32642801, 2020). "The IDH1 mutation remodels the methylome of gliomas, determined as Glioma CpG island methylator phenotype (G-CIMP), which is a powerful factor in tumor pathology." (PMID 32993063, 2020). "Gliomas with isocitrate dehydrogenase (IDH1/2) mutations have a much better prognosis and response to therapy." (PMID 33207722, 2020). "In our institute, IDH1/2 mutation status of glioma patients has been routinely available since June 2012." (PMID 33214617, 2020). "A number of important molecular biomarkers that are prognostic and/or predictive have already been identified in glioma patients including 1p19q co-deletion, IDH1 mutation, and MGMT methylation." (PMID 32355162, 2020). "The glioma patients with mutated IDH-1 (p = 0.042) or 1p/19q codeletion (p = 0.017) were found to have relatively low levels of CSF sPD-L1." (PMID 32038986, 2020). "Our detailed characterization of the immune content of different gliomas suggests that the presence of IDH1/2 mutations, even more than the histological grading, is the best predictor of a reduced immune infiltration in gliomas." (PMID 33147752, 2020). "On the other hand, IDH2 mutations occurred less frequently in gliomas and were mutually exclusive of IDH1 mutations." (PMID 31963897, 2020).